EGFR (epidermal growth factor receptor)
Diseases named in the same sentence as EGFR in open-access papers (continued):
Sharing a sentence is not in itself a finding about the gene and the disease.
cancer (continued). "For these reasons, EGFR and its downstream signaling molecules are considered as targets for therapeutic interventions in cancer." (PMID 31921216, 2019). "Resistance to the other anti-EGFR therapies can also occur through anti-stress mechanisms by cancer cells to overcome the cytotoxic effects of anti-EGFR therapies." (PMID 31527477, 2019). "Because transducer and activator of transcription 3 (STAT3) contributes to cancer stemness and EGFR-TKI survival, we assume that STAT3 plays a major role in the regulation of HER3 expression." (PMID 31619200, 2019). "Cetuximab conjugated TH (THC3) with intercalated doxorubicin (DOX) drug i.e. THDC3 showed preferential killing of MDA-MB-468 cancer cells, due to cetuximab which is known to target EGFR over-expressing cancer cells." (PMID 31661003, 2019). "Compared with the first generation TKIs, afatinib has demonstrated 100-fold greater binding to T790 M-mutant EGFR cancer cells." (PMID 30975211, 2019). "Inhibition of EGFR signaling with gefitinib results in growth delay of cancer cell lines expressing high levels of EGFR via activating FOXO3a by dephosphorylation, thus allowing its nuclear translocation." (PMID 30478887, 2019). "EGFR-mediated expression of MMPs is upregulated in most cancers, which has crucial roles in invasion and metastasis." (PMID 31579447, 2019). "Abnormal activation of the epidermal growth factor receptor (EGFR) by mutation or overexpression leads to the development and progression of cancers in various organs." (PMID 31703435, 2019). "The development of small-molecule inhibitors and mAbs for the targeted treatment of EGFR+ cancers has been an exciting area of research in recent years." (PMID 30975211, 2019). "EGFR overexpression in HNC is also observed in normal tissue adjacent to the cancer, which supports the notion of field cancerization." (PMID 30700700, 2019). "Acquired resistance to EGFR targeted anti-cancer tyrosine kinase inhibitors (TKIs), is often observed in LC patients due to mutations of EGFR." (PMID 31623614, 2019). "To investigate the role of ANXA2 in the regulation of EGF/EGFR signaling, we established cancer cell lines depleted of ANXA2 (A549, HT1080 and MDA-MB-231 ANXA2 knockdown (KD)) and respective controls (ANXA2 scramble)." (PMID 30959964, 2019). "It is believed that this work would be giving a reference for developing of anti-cancer drugs targeted EGFR-TK." (PMID 31530043, 2019). "With this work, we show for the first time, that depletion of ANXA2 in cancer cells leads to enhanced activation of AKT in response to either EGF/EGFR activation or oncogenic H-RasV12 transformation." (PMID 30959964, 2019). "Stimulation with EGF, a major chemoattractant for invading cancer cells, results in activation of EGFR downstream signaling pathways." (PMID 31649529, 2019). "In this same study, exogenous expression of EGFR can protect cancer cells from E1A inducted apoptosis." (PMID 31817939, 2019). "Two classes of EGFR inhibitors have been developed for cancer therapy: 1) reversible tyrosine kinase inhibitors, including gefitinib and erlotinib; and 2) EGFR blocking antibodies, including cetuximab and panitumumab." (PMID 30921351, 2019). "As is well known, EGFR can activate numerous intracellular signaling pathways that promote cancer cell proliferation and survival via stimulating transcription of many genes involved in these pathways." (PMID 30922269, 2019). "Small compounds accelerated and enhanced EGFR and associated proteins degradation during EGF and/or glutamine starvation of cultures, thereby demonstrating high potency in killing cancer cells by simultaneously modulating signaling and metabolic pathways." (PMID 31374910, 2019). "The EGFR inhibitor AST1306 reversed the RRM2-induced effects on cancer cells, indicating that the function of RRM2 is associated with EGFR/AKT signaling pathway." (PMID 31696057, 2019).
cancer (continued). "Additionally, exoDNAs contain similar mutations, such as BRAF (V600E) and mutated epidermal growth factor receptor (EGFR), as the cancer cell lines from which they originated, suggesting the potential role of exoDNAs as alternative biomarkers in the detection and diagnosis of cancers." (PMID 31078138, 2019). "Initially, EGFR expression was determined in the selected cancer cell lines by Western blotting and flow cytometry." (PMID 30213849, 2019). "These inhibitors include gefitinib and erlotinib; two oral anti-cancer treatments that act as selective inhibitors of the TK domain of the EGFR." (PMID 35582714, 2019). "In recent years, studies of FAM83A and FAM83B have established them as novel transforming oncogenes that function as intermediaries in EGFR/RAS signaling in different types of cancer." (PMID 31242643, 2019). "In particular, EGFR activation with 4-nitro-benzoxadiazole derivatives has been shown to rely on the generation of H2O2 by cytoplasmic superoxide dismutase in cancer cells." (PMID 31374910, 2019). "EGFR is overexpressed in NSCLC cells by 40–80%, underscoring the potency of EGFR inhibitors in cancer cell proliferation." (PMID 31426614, 2019). "All the results combined suggest that TKI-induced kinase-inactivated EGFR dimers have a critical function in sustaining survival of cancer cells in both intrinsic and acquired resistances." (PMID 31121829, 2019). "The results were quite surprising, because all eight studies in the cohort came from different types of cancer cell lines, EGFR inhibitors, and technology platforms." (PMID 30621238, 2019). "EGFR plays important roles in cell proliferation, apoptosis, angiogenesis, and other processes related to cancer progression." (PMID 31804974, 2019). "We have recently found that SEMA3C drives cancer growth by transactivating multiple receptor tyrosine kinases including EGFR, HER2 and MET via Plexin B1." (PMID 30759745, 2019). "Both monoclonal antibodies and small tyrosine kinase inhibitors (TKIs) to block/inhibit EGFR’s kinase activity have been developed as targeted therapies for EGFR-dependent cancers." (PMID 31121829, 2019). "Anti-EGFR antibodies e.g. cetuximab, panitumumab and nimotuzumab are used to treat different EGFR positive cancers." (PMID 30800216, 2019). "The efficacy of EGFR antagonists against HCC has been demonstrated in cancer cell lines and animal models." (PMID 31635301, 2019). "Over the past decades, various EGFR inhibitors (erlotinib hydrochloride, cetuximab, and necitumumab), have been approved for cancer treatment." (PMID 31546749, 2019). "Overexpressed activity of the epidermal growth factor receptor (EGFR) family has been found in many human cancers." (PMID 31847192, 2019). "We further asked how increased serine production contributes to the malignant growth of EGFR-dependent cancer cells." (PMID 31221965, 2019). "We explore the interconnectivity between Pyk2 and EGFR signaling pathway in different cancer types, as well as aid in the identification of potential targets for cancer therapy." (PMID 31368612, 2019). "EGFR antagonists were one of the first anti-cancer treatments developed targeting a receptor tyrosine kinase." (PMID 30659329, 2019). "A large number of cancer-relevant genes with specific clinical significance have been identified, such as epidermal growth factor receptor (EGFR), KRAS, ERBB2, BRAF, and PIK3CA4." (PMID 31729406, 2019). "Consequently, the intrinsic cell-to-cell variation in the EGFR mutation status might be masked by bulk-cell examination and the mutation status of EGFR might be misinterpreted due to the interference from the genetic heterogeneity of the cancer cells." (PMID 31014278, 2019). "Even in those patients who do achieve an obvious cancer response to clinically used EGFR inhibitors, most will ultimately display progression and development of this disease, which implies developed resistance in these patients." (PMID 31013819, 2019).
cancer (continued). "Positive expression of HER2/c-erbB-2 and EGFR proteins in cancer tissue was significant higher than normal gastric tissue and have significant correlation with prognosis." (PMID 33817143, 2019). "One possible explanation is that Tks4 is involved in the regulation of cancer cell motility, as indicated by its roles in EGFR signaling an EMT-inducing molecular pathway." (PMID 31671862, 2019). "The remaining activity was prevented by an inhibitor of EGFR tyrosine kinase activity and by an inhibitor of Src, another tyrosine kinase commonly found in cancer cells as a proto-oncogene whose activation encourages cell survival." (PMID 30841571, 2019). "Activation of the EGFR tyrosine kinase induces MTHFD2 expression in some cancer, as well as normal epithelial cells." (PMID 30532069, 2019). "miR-1296-5p targets different genes and cancer pathways in different contexts; therefore, we identified two novel targets, CDK6 and EGFR, for miR-1296-5p to provide an understanding of the underlying mechanism." (PMID 30530570, 2019). "The nanoparticles were preferentially taken up into EGFR+ cancer cells (MDA-MB-468, BT-549, MDA-MB-231) over cells that were EGFR- (KPL4, MCF7), as analyzed by flow cytometry." (PMID 30875927, 2019). "This possibility is supported by the observation showing that in cancer cells EGFR exists in two types of status, a kinase activatable one and a kinase unactivatable one." (PMID 31508364, 2019). "The NGC fusion protein is composed of a biparatopic anti-EGFR nanobody for cancer cell targeting, a high-affinity gadolinium-binding domain for MRI imaging, and a C3-tag for drug conjugation." (PMID 31695800, 2019). "During this time, John Mendelsohn also continued his interest in various mechanistic aspects of EGFR's inner working in cancer cells, largely through collaborative studies with his colleagues." (PMID 31798764, 2019). "Overexpression of EGFR has been reported in cSCC, so targeting EGFR has been a promising therapeutic approach in treating this type of cancer." (PMID 31370278, 2019). "The nimotuzumab drug conjugates were evaluated in vitro and in vivo for their efficacy against EGFR-positive cancer cells and KRAS mutant mCRC mouse xenograft." (PMID 30800216, 2019). "Studies had shown that inhibition of EGFR signaling pathway directly affects the secretion of VEGF in cancer cells." (PMID 31296849, 2019). "In vivo, EGFR-GFP was also observed to be localized to the apical portion of the breaching invadopodia during cancer cell extravasation." (PMID 30651600, 2019). "Despite promising efficacy of EGFR in multiple cancer types, prediction of response against EGFR inhibition still remains ambiguous." (PMID 31635038, 2019). "The EGFR regulates important pathways such as growth, survival, proliferation and differentiation in mammalian cells, and it has become a major drug target as EGFR signaling is critical for the development of many types of cancer." (PMID 30717378, 2019). "In EGFR wild‐type A549 and H460 cells, the anti‐cancer activity of Ibr‐7 was obviously superior to that of ibrutinib, indicating different mechanisms of actions of Ibr‐7." (PMID 30663221, 2019). "Compared with the αvβ3− or the control groups, the integrin αvβ3+ cancer cells showed significant EGFR inhibitors resistance, suggesting that the expression of integrin αvβ3 are highly correlated to the EGFR-associated drugs resistance in NSCLC." (PMID 31316001, 2019). "The HER2/c-erbB-2 and EGFR positive expression rate in the cancer tissues were significantly higher than that of normal gastric tissues." (PMID 33817143, 2019). "Firstly, we explored the effect of miRNA-125a-5p on EGFR mRNA expression in cancer cells by RT-qPCR." (PMID 31759360, 2019). "The importance of optimizing dosing regimen also extends into immunotherapy or targeted anti-cancer therapy, such as EGFR inhibition." (PMID 31512089, 2019).
cancer (continued). "Together these findings suggest that the EGFR is essential for maintaining growth and preventing apoptosis in cancer cells, and up-regulation of MCL-1 is an important mechanism through which EGFR functions." (PMID 31150457, 2019). "Currently, there are two distinct therapeutic strategies employed for EGFR‐targeted cancer therapy: One is monoclonal antibodies and the other is small‐molecule tyrosine kinase inhibitors (TKIs)." (PMID 30372581, 2019). "Afterwards, it was used in combination with previously designed EGFR specific A-P-NLC (AEYLR peptide-PEG-modified paclitaxel loaded NLC) to achieve the goal to kill the cancer cells and CSCs, simultaneously." (PMID 30880491, 2019). "miR-302a restored CTX responsiveness by suppressing CD44-induced cancer stem cell-like properties and EGFR-mediated MAPK and AKT signaling." (PMID 31754405, 2019). "For example, inhibition of glycosylation sensitizes cancer cells that are resistant to EGFR targeted therapy to radiation." (PMID 31171001, 2019). "IGFBP7 confers resistance to EGFR-TKIs and is a potential therapeutic target for treating EGFR-TKI-resistant cancers." (PMID 30609749, 2019). "Molecular subtyping is a cornerstone of precision medicine in cancer treatment, and the mutation status of genes in the EGFR pathways, including RAS genes, PIK3CA, PTEN and BRAF have been shown to predict response to EGFR blockade therapy in CRC." (PMID 31775679, 2019). "We didn’t replicate the work in a mammalian model as the data already gathered appears to be sufficient to proceed to the next step -a prospective observational study of muscle fiber type changes in cancer patients treated with EGFR inhibitors." (PMID 31239465, 2019). "As previously reported, combinatorial antibody treatments against different targets induce synergistic effects; in particular, several clinical studies combining PD-L1/PD-L1 inhibitors with either ErbB2 or EGFR-TKIs in cancer patients are on-going." (PMID 31470510, 2019). "After the initial promising results of EGFR-targeted therapies such as cetuximab, therapeutic resistance poses a challenging problem and limits the success of effective anti-EGFR cancer therapies in the clinic." (PMID 30650638, 2019). "Given the fact that EGFR possesses kinase-independent pro-survival function, the role of TKI-inactivated EGFR in cancer cell survival needs to be addressed." (PMID 31121829, 2019). "Recent years have witnessed a realization that EGFR possesses kinase-independent (KID) pro-survival functions in cancer cells." (PMID 31508364, 2019). "Epidermal growth factor receptor (EGFR), a family of tyrosine kinase receptors, is frequently upregulated in human cancers." (PMID 31592235, 2019). "After forming spheroids with diameter greater than 100 μm in a 12 by 36 pillar array chip (25 mm by 75 mm), we confirmed that the A549 cell line showed overexpression of p-EGFR in cancer spheroids." (PMID 31614722, 2019). "Other noteworthy mechanisms promoting cancer cell migration include EGFR downstream activator son of sevenless (SOS) and growth factor receptor-bound protein 2 (GRB2) that increases PI3K-AKT signaling." (PMID 29478325, 2019). "MAP2K1 (also called MEK1) and EGFR were validated as negative regulators by showing that treatment of several cancer cell lines with inhibitors of either enzyme increased mRNA levels and cell surface expression of HLA-A and B2m." (PMID 31112530, 2019). "Epidermal growth factor receptor (EGFR) inhibitors have benefitted cancer patients worldwide, but resistance inevitably develops over time, resulting in treatment failures." (PMID 30621238, 2019). "Previous studies have shown that the EGFR pathway plays an important role in the proliferation, migration, and invasion of cancer cells." (PMID 30821275, 2019).
cancer (continued). "We previously demonstrated that DDA treatment kills cancer cells that overexpress EGFR and/or HER216." (PMID 31839995, 2019). "And the positive expression rate of EGFR in cancer and paired normal gastric tissues were 41.8% (28/67) and 5.9 (4/67), respectively, with statistical difference (p<0.05)." (PMID 33817143, 2019). "In conclusion, our current results suggest that TNuF is an ideal radiosensitizer, as it can inhibit cancer invasion and metastasis by targeting EGFR and VEGF signaling." (PMID 31426614, 2019). "In a recent report, the role of autophagy was assessed in the cytotoxicity induced by anti-EGFR antibody-conjugated gold nanoparticle (anti-EGFR–Au-NPs)-combined near infrared-photothermal therapy (NIR-PTT) in MDA-MB-231 cancer cells." (PMID 30483817, 2019). "Overall, these findings suggest that EGF-induced EGFR internalization and nuclear translocation in DUOX1-deficient cancer cells is associated with altered dynamics of EGFR oxidation." (PMID 30890751, 2019). "Some dual hit combinations have been approved for different pathways and cancer types, such as dual inhibition of EGFR, HER2, and MAPK." (PMID 31480389, 2019). "Gracillin displayed broad-spectrum inhibitory effects on the viability of a large panel of human cancer cell lines, including those carrying acquired resistance to chemotherapy or EGFR-targeting drugs, by inducing apoptosis." (PMID 31649278, 2019). "Cross talk and cross-activation between LR and EGFR is well documented mainly in cancer cell lines, but also in muscle, salivary gland, and mucosal cells and in rat kidneys." (PMID 30659329, 2019). "For instance, in wild-type EGFR cancer cells, AXL overexpression induces resistance to the anti-EGFR antibody cetuximab via MAPK signaling." (PMID 30651547, 2019). "The combined effects of substitution and tyrosine phosphorylation suggest that cellular context, for example overexpression of EGFR found in many cancers, will be especially important for understanding diseases modulated by the PLC-γ isozymes." (PMID 31889510, 2019). "Our data show that wild-type EGFR plays a significant role in KRAS-mutant NSCLC cancer cells and revealed CXCR7 upregulation as a potential survival mechanism in KRAS-mutant cells upon EGFR loss." (PMID 30935067, 2019). "We investigated one hundred patients who received TKIs as a first-line therapy for advanced EGFR-mutant NSCLC in a tertiary cancer center." (PMID 31728013, 2019). "We believe EGFR dynamics are coupled to the signaling networks through the local actin environment of the cancer cells, and changes in cancer cell behaviors, such as epithelial-mesenchymal transition, can alter the EGFR dynamics." (PMID 30833579, 2019). "In vitro cytotoxicity studies with the MMAE-Pep11 conjugate demonstrated that this peptide-drug conjugate can selectively kill EGFR overexpressing cancer cells while having lower toxicity towards non EGFR expressing normal cells." (PMID 30700733, 2019). "This new knowledge has offered a different angle of understanding of EGFR in cancer and opened a new avenue of targeting EGFR for cancer therapy." (PMID 31508364, 2019). "Inhibiting the tyrosine kinase activity of epidermal growth factor receptor (EGFR) using small molecule tyrosine kinase inhibitors (TKIs) is often ineffective in treating cancers harboring wild-type EGFR (wt-EGFR)." (PMID 31121829, 2019). "The increase in the difference of cytotoxicity of MMAE-Pep11 and MMAE to cancer cells and normal cells showed the selectivity of peptide-drug conjugate and form the basis for targeting the delivery of MMAE to EGFR expressing cancer cells." (PMID 30700733, 2019). "Together, the eight PTK inhibitors block most of the cancer census PTKs, including members of the Abl, Src, EGFR, FGFR, VEGFR, and PDGFR families." (PMID 30754629, 2019).